NDUFB1 (NADH:ubiquinone oxidoreductase subunit B1)
Description:
Accessory subunit of the mitochondrial membrane respiratory chain NADH dehydrogenase (Complex I) that is believed not to be involved in catalysis. Complex I functions in the transfer of electrons from NADH to the respiratory chain. The immediate electron acceptor for the enzyme is believed to be ubiquinone.
Synonyms: CI-MNLL; MNLL; CI-SGDH
Tractability: Small molecule: an approved drug acts on it; a structure with a bound ligand is known. Antibody: UniProt predicts a signal peptide or a membrane-spanning region. PROTAC: ubiquitination databases record sites on it; its protein half-life has been measured.
Gene: Protein-coding gene on chromosome 14 (92,116,119 to 92,121,978, reverse strand). Ensembl gene ENSG00000183648.
Subcellular location: Mitochondrion inner membrane
Subcellular location (Human Protein Atlas): Mitochondria; Nuclear speckles
Pathways (Reactome):
Metabolism: Complex I biogenesis; Respiratory electron transport
Gene Ontology:
Molecular function: NADH dehydrogenase (ubiquinone) activity
Biological process: aerobic respiration; mitochondrial electron transport, NADH to ubiquinone; proton motive force-driven mitochondrial ATP synthesis; proton transmembrane transport
Cellular component: mitochondrial inner membrane; mitochondrion; respiratory chain complex I
Genetic constraint (gnomAD): Loss-of-function variants: 6 observed, 7.13 expected, observed/expected ratio (o/e) 0.84, 90% interval 0.46 to 1.61. That is too few expected variants to judge how well the gene tolerates losing a copy. Missense variants: 56 observed, 72.6 expected, observed/expected ratio (o/e) 0.77, 90% interval 0.62 to 0.96. Synonymous variants: 17 observed, 23.13 expected, observed/expected ratio (o/e) 0.73, 90% interval 0.5 to 1.1.
Homologues: Orthologues: chimpanzee NDUFB1 (100% identical), macaque NDUFB1 (93% identical), pig NDUFB1 (83% identical), dog NDUFB1 (79% identical), rat Ndufb1 (76% identical), mouse Ndufb1 (74% identical), tropical clawed frog ndufb1 (72% identical), zebrafish ndufb1 (66% identical).
Diseases named in the same sentence as NDUFB1 in open-access papers:
NDUFB1 is named in the same sentence as 15 diseases in open-access papers, as found by Europe PMC text mining. Sharing a sentence is not in itself a finding about the gene and the disease. The quoted sentences say what the papers report.
breast carcinoma (3 papers, 2015 to 2025). "Elevated NDUFB1 expression correlated with improved relapse-free survival in breast cancer, while its regulation by TNF-α differed between ER-positive and triple-negative cell lines." (PMID 41157129, 2025). "For example, multiple Complex I subunits, such as NDUFB1, NDUFS4, NUBPL, and NDUFA7, have been implicated in the metabolic plasticity of breast cancer cells." (PMID 41157129, 2025). "In addition, we also observed that the majority of other subunits (NDUFB1-8/11) from the NADH dehydrogenase family have significant prognostic value (DMFS) in breast cancer patients, indicating the considerable clinical value." (PMID 26641458, 2015). "Genes such as NDUFB1, NDUFB2, and NDUFB7 were found to have significant prognostic values for breast cancer patients." (PMID 32785169, 2020).
Huntington disease (3 papers, 2016 to 2025). Huntington disease (HD) is a rare neurodegenerative disorder of the central nervous system characterized by unwanted choreatic movements, behavioral and psychiatric disturbances and dementia. "However, together with NDUFB1, COX17, and ATP5MC1, they were reported as upregulated in patients with Parkinson’s, Alzheimer’s, and Huntington’s diseases." (PMID 41296444, 2025).
clear-cell renal cell carcinoma (2 papers, 2024 to 2025). "For instance, NDUFB1 mRNA was reported to be downregulated in aggressive ovarian cancers, suggesting a reduction in oxidative phosphorylation in high-risk tumors, whereas altered transcript levels were also detected in clear-cell renal cell carcinoma." (PMID 41157129, 2025). "NDUFB1 and NDUFA3 were reported to be associated with the OXPHOS pathway exhibited alterations in clear-cell renal-cell carcinoma and lung squamous cell carcinoma." (PMID 38698303, 2024).
hypertrophic cardiomyopathy (1 paper, 2024). A condition in which the myocardium is hypertrophied without an obvious cause. "NDUFB1 and NDUFB2 are associated with altered cardiac energetics and mitochondrial dysfunction in patients with hypertrophic cardiomyopathy, and ROMO1 is an essential redox-dependent regulator of mitochondrial dynamics." (PMID 38396938, 2024).
ovarian carcinoma (1 paper, 2025). A malignant neoplasm originating from the surface ovarian epithelium. "Although NDUFB1 has not been validated as an independent biomarker, it has appeared in multi-gene prognostic signatures, such as a poor-prognosis ovarian cancer panel incorporating low NDUFB1 expression." (PMID 41157129, 2025).
tumor (2 papers, 2025). "The Acetalax comparison using the tumor size as continuous values found significant correlation for NDUFB1 (P = 0.038)." (PMID 39932272, 2025). "In general, perturbations of Complex I function, including those involving NDUFB1, affect the NAD+/NADH balance, modulate reactive oxygen species production, and contribute to the metabolic switch characteristic of tumor cells." (PMID 41157129, 2025).
cancer (1 paper, 2025). A tumor composed of atypical neoplastic, often pleomorphic cells that invade other tissues. "In particular NDUFB1—an accessory, non-catalytic subunit of mitochondrial Complex I, which contributes to the assembly and stabilization of Complex I. Dysregulation of Complex I subunits, including NDUFB1, is frequently observed in cancer, reflecting metabolic rewiring of malignant cells." (PMID 41157129, 2025).
neurodegenerative disease (1 paper, 2025). A disorder of the central nervous system characterized by gradual and progressive loss of neural tissue and neurologic function. "The mitochondrial dysfunction in the neurodegenerative diseases cluster (Cluster 4) comprises 95 genes, including several key mitochondrial protein genes acting as pivotal hub genes, such as Sdhb, Ndufa4, Ndufb4c, Ndufb4b, Ndufv3, Ndufa9, Ndufc1, Ndufs5, Ndufb4, Ndufa12, Ndufa11, and Ndufb1." (PMID 41294802, 2025).
NDUFB1 also shares sentences with these, for which no sentence is quoted: Parkinson disease (3 papers); Alzheimer disease (1); lung adenocarcinoma (1); lung carcinoma (1); lung squamous cell carcinoma (1); non-alcoholic fatty liver disease (1); Parkinson’s (1).